IFNG (interferon gamma)
Diseases named in the same sentence as IFNG in open-access papers (continued):
Sharing a sentence is not in itself a finding about the gene and the disease.
tumor (continued). "Once they reach the tumor, the CD4+ T-cells release cytokines like IFNγ and TNF to enhance the cytotoxic CD8+ T-cell-mediated response, strengthening the antitumor immune response." (PMID 38002256, 2023). "In ex vivo patient-derived tumor cultures, a PSGL-1 blocking antibody increased expression of macrophage-derived proinflammatory cytokines, as well as IFNγ, indicative of T-cell activation." (PMID 37819238, 2023). "PD-L1 expression in tumor cells correlates with the intestinal type, number of CD8+T cells and macrophages in the TME of GC, and IFN-γ expression in tumor cells correlates to the presence of suppressive CTLA-4+/IFNγ+ immune cells in the TME and the lymph node." (PMID 36979688, 2023). "CD4+ T-cell activation (via tumor-specific MHC II) leads to increased interferon-gamma (IFN-γ) secretion, thus enhancing CXCL9 production and PD-L1 expression, culminating in an immunotherapy-sensitive tumor phenotype." (PMID 37761972, 2023). "Cancers expressing DUX4 had diminished IFNγ-induced MHC class I expression, reduced anti-tumor immune cell infiltration, and showed resistance to immune checkpoint blockade." (PMID 37092726, 2023). "Effector T cells also produce cytokines such as interferon-gamma (IFN-γ) and tumor-necrosis factor alpha (TNF-α) leading to tumor cell apoptosis." (PMID 38550850, 2023). "Upon treatment with conditioned medium from tumor cells, the IFNγ levels of CD8+ T cells were greatly increased in both groups, while only the neutrophils primed by Setd2KO cells were able to reduce IFNγ, and surface PD‐1 levels in CD8+ T cells." (PMID 36453584, 2023). "Analysis of intratumoral lymphocytes in sgSlc38a2-transduced MC38 tumours revealed a higher frequency and number of intratumoral CD8+ T cells, including those expressing IFNγ, TNF or granzyme B, indicative of enhanced effector phenotypes." (PMID 37407815, 2023). "Despite the close connections of IFNG and co-expressed genes with the TME and immune checkpoint molecules, their roles in anti-tumor immunity need experimental verification." (PMID 37408777, 2023). "ICI-treated or control CT26-bearing BALB/c mice received ~200 μCi [89Zr]Zr-DFO-anti-IFNγ, PET imaging was conducted, and tumor volumes were monitored until they reached an experimental endpoint of ≥ 100 mm3." (PMID 38130991, 2023). "Intriguingly, these modified T cells are capable of secreting cytokines such as Interferon-gamma (IFN-γ), thereby bolstering endogenous CD8+ T-cell responses and eliciting a more robust immune response against the tumor." (PMID 37760801, 2023). "Data on the role of TYRO3 in macrophage polarization are scarce with one study showing that TYRO3 can inhibit lipopolysaccharide (LPS) and interferon-gamma (IFN-γ)-induced M1 polarization of peritoneal and tumor-derived mouse macrophages." (PMID 38203403, 2023). "Z. multiflora essential oil (500 mg/kg) reduced tumour weight and balanced T helper 1 levels by increasing the secretion of TNF‐α, Interferon‐gamma (IFN‐γ) and IL‐2 and decreasing IL‐4 levels." (PMID 37697969, 2023). "When cocultured with tumor cells overexpressing BHLHE40, CD8+ T-cell apoptosis was increased, the number of IFNγ+CD8+ T cells was significantly decreased, and the number of PD-1+CD8+ T cells was significantly increased." (PMID 37377917, 2023). "The combination therapy increased the infiltration of CD8+ T cells, and the percentages of IFNγ+, TNFα+ CD8+ T cells and the percentages of IFNγ+, TNFα+ CD4+ T cells in the tumor microenvironment." (PMID 37553341, 2023). "Concurrent secretion of interferon gamma (IFN-γ) and tumor necrosis factor (TNF) by cytotoxic CD8+ T lymphocytes leads to a compromise in the integrity of tumor-resident blood vessels, and an ischemic state of the tumor is generated and sustained." (PMID 37345111, 2023). "Radiotherapy-activated ATM and IFNγ-induced STAT1 signalling jointly repress SLC7A11 to reduce cystine uptake and enhance tumor lipid peroxidation and ferroptosis." (PMID 37714846, 2023).
tumor (continued). "These NK cells were able to lyse tumor cells because they upregulate their transcription and release of granzyme B (GZMB) and interferon-gamma (IFN-γ)." (PMID 37131214, 2023). "A significant decrease in levels of interferon γ (IFNγ), IL1β, interleukin 8 (IL8) and monocyte chemoattractant protein-1 (MCP1) was identified in both gas plasma-treated WT and RE tumours." (PMID 37460712, 2023). "CD8+ T lymphocytes mediate cytotoxic responses by releasing inflammatory factors like Interferon-gamma (IFN-γ) and TNF-α, inhibiting tumor growth, proliferation, and metastasis." (PMID 37901310, 2023). "In agreement with PARP14 being an IFNγ target gene, we observed PARP14 levels increasing in response to higher doses of IFNγ in multiple human and mouse tumour cell lines." (PMID 37752135, 2023). "The effect of chronic IFNγ exposure on and possible contribution of PARP14 to tumour infiltration by myeloid and helper T cell populations also merits further investigation." (PMID 37752135, 2023). "They secrete IFNγ in response to IL-12 within the TME which can exert anti-tumor affects by inducing tumor cell death and preventing tumor growth." (PMID 38567059, 2023). "Strikingly, we observed that overexpression of IFI35 promoted CD8+ T cells to secrete more IFNγ and TNFα in CT26 tumor." (PMID 37380972, 2023). "Two inflammatory factors IFNγ and CCL2 were elevated in the liver after YB1 administration, but only IFNγ was found to be responsible for the anti-tumor effect." (PMID 38020179, 2023). "IFNγ enhanced PD-L1 and IDO expression in various tumors, which killed T cells and led to tumor immune escape." (PMID 37175461, 2023). "Rather, we noticed that tumor-infiltrating CAR T cells with BATF3 OE expressed higher levels of both TCF1 and IFNγ." (PMID 37945901, 2023). "LPS-induced TLR4 alone or in combination with IFNγ activates the PI3K-mTOR-AKT (phosphoinositide-3-kinase-mammalian target of rapamycin) pathway, which leads to the polarization of anti-tumor M1 macrophages and the suppression of cancer cell proliferation." (PMID 38035101, 2023). "T-cell receptor (TCR) sequencing on matched PBMCs and tumor biopsies from patients with high/medium increase in serum IFNγ demonstrated increased T cell density and TCR diversity at the tumor site, indicative of augmented T cell homing into the tumor." (PMID 38260854, 2023). "By activating the GNAS-PKA axis, MC1R inhibits interferon-gamma induced CXCL9/10/11 transcription, thus impairing T cell infiltration into the tumor microenvironment." (PMID 37714844, 2023). "Through the secretion of interferon-gamma (IFN-g), NK cells exert a substantial impact on tumor structure and the spread of cancer cells, thereby highlighting their indispensable contribution to the immune landscape within tumors." (PMID 38332915, 2023). "The superior intracellular delivery and lymph node homing of V-scVLPs significantly enhanced IFNγ+CD8+T-cell infiltration and TCM memory phenotype, which prevented the orthotopic tumor growth and prolonged animal survival in a prophylactic setting." (PMID 37554274, 2023). "At the tumor site, mice consistently displayed high percentages of tumor-infiltrating CD8+ cells, elevated levels of IFNγ expression in effector CD4+ and CD8+ T cells, and a substantial loss of Tregs." (PMID 37189748, 2023). "Using Reactome for pathway enrichment analyses, we observed Trp2Vax and immunotherapy treatment upregulated the IL-12 responsive genes, including ITGB1, SOCS3, IFNG and STAT4 in the tumor-infiltrating CD4+ T cells (with a False Discovery Rate, FDR= 0.0016)." (PMID 36911698, 2023). "They found that the anti-tumor activity of the CAR-T cells was related to the upregulation of CXCR-1/2 and appropriate IFNγ production." (PMID 37443804, 2023). "Whilst the PD-L1 blockade inhibited effector T cell dysfunction, IL-12 polarised naïve T cells towards the Th1 subset in the presence of IFNγ (produced by the CAR-T cells), contributing towards the anti-tumour response." (PMID 39935547, 2023).
tumor (continued). "We had available 19 tumor dissociates matched with our PD1 PROG cell lines, including five showing intrinsic baseline IFNγ activity." (PMID 36934113, 2023). "The main agents of antitumor immunity, CD8 T cells secrete IL-2, IL-12, and (IFNγ) in TME, which increases the ability of CD8 T cells to target and destroy tumor cells." (PMID 37213276, 2023). "The treatment of leukemia mice with Tie2-monocytes, engineered for the release of IFNγ and TNFα, induced the activation of the CD8 + effector T cells, but also of MHC II + memory T cells and significantly delayed tumor progression." (PMID 36854896, 2023). "Although the CD4+ TILs also remained stable in the combination group, the proliferation of CD4+ T cells, the Th1/Th2 ratio as well as IFNγ+ CD4+ TILs also increased, indicating an increase of tumor-specific CD4+ T cells by the combination treatment." (PMID 37771774, 2023). "Co-culture of tumor models with anti-HER1 CAR-NK-92 cells led to enhanced degranulation and IFNγ secretion of NK-92 cells and apoptosis of target cells." (PMID 37370779, 2023). "Although we demonstrate the possibility of application of anti-IFNγ antibody to restore vascular integrity for drug delivery in this study, the neutralising anti-IFNγ antibody might have dosage-dependent effects on the treatment of tumour that needs further studies in different treatment conditions." (PMID 37056922, 2023). "Instead, we leveraged the properties of native HSA to target tumor tissue using the FHAB platform to extend the PK of IL-12 in humans, resulting in prolonged but controlled induction of IFNγ and decreased toxicity." (PMID 38250068, 2023). "To further explore the activating phenotypes of tumor-infiltrating T cells induced by HK010, we detected the expression of Ki-67, IFNγ, and CD8 in tumor tissues according to a previous study." (PMID 37259060, 2023). "Functional assessment reveal interferon gamma (IFNγ) as a key mediator of CAR T-cell cytotoxicity and recursive tumor cell killing in vitro, and further validate the role of IL-12 in potent IFNγ induction and downstream CAR T-cell activity." (PMID 37550294, 2023). "The development of cytotoxic CD8+ T lymphocytes requires antigen cross presentation by XCR1+ cDC1 cells and tumor-infiltrating potential, a program driven by type 1 cytokines such as IL12 and IFNγ." (PMID 37833072, 2023). "To examine the impact of intrinsic IFNγ signaling within the tumor microenvironment, we applied multiparameter flow cytometry analysis of PD1 PROG tumor dissociates." (PMID 36934113, 2023). "CD8+ T cells promote ferroptosis in tumor cells by releasing interferon-gamma (IFN-γ) and suppressing the expression of SLC3A2 and SLC7A11 in tumor cells." (PMID 37238692, 2023). "Over time, Cxcr3 and Klrg1 were progressively decreased on tumor-specific T cells infiltrating PDA and these Cxcr3-Klrg1- T cells co-expressed PD-1 and Lag-3, markers that identify TEX cells defective in IFNγ production." (PMID 36472588, 2023). "Cytokine negatively regulates IFNγ signaling through CSF1R expression, thus modulating the functions of tumor infiltration." (PMID 35433686, 2022). "The interaction between IFNγ and CD8+ T cells in the TME plays an important role in anti-tumor immune responses induced by ICIs." (PMID 35053427, 2022). "IFNγ expression after IRE treatment due to T cell activation and PD1 by T cells and PD-L1 by tumor cells have been shown, but it is poorly understood what pathway is being activated and requires further investigation." (PMID 35372046, 2022). "This acidification has been shown to reduce anti-tumor CTL activation, glycolysis, and expression of functional markers such as IFNγ via diminished NFAT signaling." (PMID 35039633, 2022). "Given that IFNγ is often released by activated CD8+ T cells, recent studies have examined how far IFNγ can reach within the tumor microenvironment." (PMID 34385592, 2022).
tumor (continued). "GSEA analysis of our RNA-seq data from the PSaRC318 tumor at relapse demonstrated upregulation of multiple immunoregulatory pathways including TNFα/NFκB, inflammatory response, TGFβ, IL6, IL2, and IFNγ." (PMID 36187937, 2022). "Meanwhile, activated CD8 + T cells release IFNG to activate the JAK-STAT1 pathway in tumor cells to inhibit the expression of system Xc -, and make tumor cells sensitive to pro-apoptotic stimuli, thereby exerting anti-tumor effects." (PMID 35692844, 2022). "We also identified unique signatures in tumour samples after VV-αCEA TCE treatment, including increased levels of CCL1, IFNγ, IL-1a, IL-1b, TIMP-1, and TREM-1." (PMID 36405739, 2022). "Tumor vaccines also boost CD4 + T cell-derived secretion of TH1-characteristic tumoricidal cytokines (e.g., IFNγ), which have direct anti-tumor activity." (PMID 36316782, 2022). "The addition of rapamycin preserved antigen-specific CD8+ tumor-infiltrating lymphocytes (TIL) and enhanced IFNγ secretion in both peripheral and infiltrating CD8+ T cells, leading to upregulation of MHC class I expression." (PMID 35372020, 2022). "Regarding antitumor therapy, CpG in conjunction with an anti-TLR2 antibody have been shown to induce the production of IFNγ and the migration of CD8 T and NK lymphocytes to the tumor stroma." (PMID 36365602, 2022). "Interferon-gamma (IFN-γ) and Interleukin-12 (IL-12), known as Th1-related cytokines serving as tumor suppression microenvironments, decreased slightly in MB49 implanted mice, but increased effectively in PLAG and aPD-L1 treated mice." (PMID 35787261, 2022). "IFNγ derived from CD8+ T cells activated by immunotherapy and ATM activated by radiotherapy synergistically inhibit SLC7A11, inducing ferroptosis in tumor cells." (PMID 36072803, 2022). "IFNγ stimulates the expression of MHC-I and MHC-II in tumor cells and APCs, enhances IL-12 production by APCs, facilitates Th1 polarization, and promotes T-cell and NK cell tumor trafficking via Th1-type chemokine production in the tumor microenvironment." (PMID 34385592, 2022). "GSEA analysis shown that several immune and tumor-related terms were enriched in ZFP36L2-high expression cohort, including epithelial mesenchymal transition, interferon alpha response and interferon gamma response." (PMID 35910229, 2022). "The data on anti-RANKL/anti-PD1/anti-CTLA4 combination therapy showed promising results in a higher proportion of tumor-infiltrating CD4+ and CD8+ T cells that can produce both IFNγ and TNFα after anti-RANKL treatment." (PMID 35386705, 2022). "Four genes (IFNA1, IFNG, LEP, and PLG) were excluded from analysis because their PCR Ct values were greater than 32 for both tumor and control samples, indicating that the expression of these genes was extremely low and not reliable for comparison analysis." (PMID 35600354, 2022). "For optimal tumor control, it has been found that IL12 exerted from Batf3 DCs is the premise for effective NK cell function and production of IFNγ." (PMID 35626062, 2022). "Using a linear correlation approach between immunotype and the SGR for each tumor, we observed tumor growth inhibition was most strongly correlated with higher levels of HLA-DR+TIM-3-TNFα+ and TNFα+IFNγ+ CD4+ T cells." (PMID 36419897, 2022). "In the majority of tumor types, NMNGs had a positive correlation with TNFA signaling via NFKB, KRAS signaling, interferon-gamma response, inflammatory response, and EMT." (PMID 36726460, 2022). "Consistent with an IFNγ-driven upregulation of MHC molecules, we also observed increased expression of PD-L1 on tumor cells with Ca alone and in combination with N." (PMID 36419897, 2022). "Using crude lung tissue samples, we expectedly observed a pronounced reduction of IFNγ+ and IL-17+ T cells in the AT3-gcsf tumor-bearing mice compared to the AT3-bearing or naïve control mice, by ICS (left)." (PMID 35126389, 2022).
tumor (continued). "Activation of T-cell immune response after interaction with tumor cells increases the production of interferon-gamma (IFN-γ), which stimulates PD-L1 membrane expression in tumor cells." (PMID 35992118, 2022). "More surprising was the ability of CAR T cells to progressively strengthen their interaction with tumor cells that initially expressed low levels of ICAM-1 and to do so in an IFNγ-dependent manner." (PMID 36189315, 2022). "TGF-β and IL-10 expression decrease synthesis of IFNγ and TNF-α by pro-inflammatory CD4 T cells, and in turn reduce tumor-specific cytotoxicity of CTLs, prevent activities of dendritic cells and NK cells, and result in tolerance to tumor cells." (PMID 35372046, 2022). "And they also proved IFNγ downregulated the mRNA expression levels of both SystemXc− subunits, leading to decreased GSH levels and inducing ferroptosis in tumor cells." (PMID 36684424, 2022). "Cocultures of tumor organoids, autologous fibroblasts and T cells allowed to observe a costimulatory effect of anti-FAP-4-1BBL both to release IFNγ and to attain more efficacious tumor cell killing." (PMID 35154495, 2022). "We further analyzed the tumor-upregulated target proteins of STAT1 and STAT2, and found these target proteins were mainly enriched in interferon gamma signaling, and response to immune." (PMID 35440542, 2022). "We have previously demonstrated that responsiveness to IFNγ and induction of MHCII in the tumor cells are important determinants of response to anti-PD-1 therapy in KRas-driven lung tumors." (PMID 36686777, 2022). "In the B16F10 tumor model, the proportion of CD3+ cells was unchanged, while CD8+ and activated CD8+ T cells, which express IFNγ (CD8+IFNγ+), were significantly increased in L/L mice." (PMID 36224346, 2022). "Phosphorylated ITAMs result in NK cell degranulation, cytokine release, and tumor cell lysis by inducing TNF, FasL, and TRAIL death receptors, IFNγ secretion, granzyme and perforin release, caspase 8 activation and apoptosis." (PMID 36686835, 2022). "Our study supports previous, and arguably understated, findings showing the crucial roles played by both IFNγ signaling on host cells and antigen presentation by TAMs for CD4-mediated tumor rejection." (PMID 35903540, 2022). "Apigenin treatment produced stronger activation of anti-tumor CD8+ cytotoxic cells and greater production of anti-tumor cytokines IFNγ, TNFα, and granzyme B in the blood than luteolin." (PMID 36555392, 2022). "Anti-PD-L1 antibody administration suppressed tumor growth in the chimeras and resulted in the increased abundance of IFNγ+CD8+ and IFNγ+CD4+ T cells and decreased abundance of PD-1+CD8+ and PD-1+CD4+ T cells in dLNs." (PMID 35217706, 2022). "In the tumor microenvironment (TME), IFNγ induces the expression of genes essential for antigen processing and presentation, thereby promoting immune-surveillance." (PMID 35902886, 2022). "One in vitro study showed that CD8 + CD103 + T cells produce higher levels of IFNγ and TNF when co-cultured with tumor cells and had higher expression of PD-1, TIGIT and CD39 in comparison to CD103- T cells." (PMID 34743182, 2022). "Here again, the connection between IFNγ produced by antigen-primed CAR T cells and the subsequent productive interaction leading to tumor cell death was demonstrated." (PMID 36189315, 2022). "The combination therapy also enhanced the presence and activation of interferon-γ (IFNγ)-expressing CD8 + cytotoxic T lymphocytes (CTLs) in tumor tissue, supporting tumor regression." (PMID 35392964, 2022). "IL-10 in the tumor microenvironment inhibits the production of IFNγ and TNFα; it also downregulates MHC class II in monocytes, establishing TIL anergy, and, in doing so, it enhances tumor growth." (PMID 35203636, 2022). "Interferon-gamma (IFNG) secreted by cytotoxic T lymphocyte inhibits the function of CTL by increasing the expression of tumor cell PDL1, leading to tumor immune evasion." (PMID 35508972, 2022).